GSTP1 (glutathione S-transferase pi 1)
Diseases named in the same sentence as GSTP1 in open-access papers (continued):
Sharing a sentence is not in itself a finding about the gene and the disease.
cancer (continued). "Another covalent inhibitor, GS-ESF, targets the G-site of GSTP1, while NBDHEX also acts covalently to modify the enzyme’s active site and trigger apoptosis in cancer cells." (PMID 39954068, 2025). "By reducing GSTP1 levels, SMURF2 disrupts this protective mechanism, sensitizing cancer cells to ferroptotic cell death." (PMID 39697237, 2024). "It has also been reported to act as a glutathione S-transferase P1-1 (GSTP1-1) inhibitor and a WNT inhibitor and exhibit anti-tumor effects in a range of cancer cells." (PMID 39063039, 2024). "In other studies, NBDHEX allosterically binds to GSTP1 leading to activation of JNK via the interaction of the JNK-GSTP1 axis, and the conformation of GSTP1 is modulated upon binding to certain anti-cancer drugs." (PMID 37491277, 2023). "Hence, especially given a crucial role of GSTP1 in receiving and forwarding the lactic acid signaling as we unravel, intervention targeting the GSTP1 protein could impede multiple metabolic pathways in diverse cancers." (PMID 37491277, 2023). "We, for the first time, show that the tumor metabolic microenvironment lactic acid activates a “signalosome” comprising GSTP1, SRC and G6PD by attenuating the complex, which facilitates a reprogrammed PPP to promote cancer cell growth." (PMID 37491277, 2023). "This nitrobenzoxadiazole (NBD) derivative is a potent mechanism-based inhibitor of both human GSTP1-1 and GSTM2-2 and exhibits remarkable cytotoxicity towards various cultured cancer cell lines (IC50 values in the low micromolar/submicromolar range)." (PMID 35215282, 2022). "The expression level of GSTP1, FAM83H, TP53AIP1, and PKP3 were all reported to be involved in the development of cancer or affecting patients’ survival rate." (PMID 35776767, 2022). "Altogether, piperlongumine can be considered as a promising anti-cancer bioactive agent that acts through the downregulation of c-Met, STAT3, NF-κB, PI3K/Akt, and ERK/MAPK signaling pathways, inhibition of GSTP1, and upregulation of hTRPV2." (PMID 36428575, 2022). "The fourth group, which was consistently identified as cancer by SRS images, contained highly expressed OSCC marker genes including GSTP1, AKR1B10, FTH1, and FTL." (PMID 35776767, 2022). "In conclusion, recent studies have established the role of GSTP1 and other GST isozymes in cancer development, progression, metastasis, and resistance to antineoplastic drugs." (PMID 33946704, 2021). "Given the involvement of GSTs in deactivating and detoxifying carcinogens, deletions in GSTM1 and GSTT1 and IIe105Val polymorphism in GSTP1 resulting in no enzyme activity may compromise an individual’s ability to deactivate carcinogens, thus increasing risk of cancer." (PMID 32155154, 2020). "TW-1 expressed various markers that are unique in stem cell, such as CD133, GSTP1, CD44, and EpCAM, which was identified as a cancer cell line with progenitor or stem cell-like properties." (PMID 33322441, 2020). "In this study, we found that both NQO1 and GSTP1 were overexpressed in GBM and functioned to inhibited oxidative stress and prevent cancer cell death." (PMID 33087132, 2020). "Inactivation of both NQO1 and GSTP1 with siRNA or MNPC results in imbalanced redox homeostasis, leading to apoptosis and mitigated cancer proliferation in vitro and in vivo." (PMID 33087132, 2020). "The proportion of CML cancer attributable to the interaction of smoking and GSTM1 null was 42% and was 39%, 13% for GSTT1 null and GSTP1 M*, respectively." (PMID 31111691, 2019).
cancer (continued). "The proportion of CML cancer attributable to the interaction of smoking and GSTM1 null, GSTT1null, and GSTP1 M* was 42%, 39%, and 13%, respectively." (PMID 31111691, 2019). "Subgroup meta-analysis by geographical populations was performed for p16, RASSF1A, GSTP1, APC and RUNX3 between HBV-positive carcinoma tissues and HBV-negative carcinoma tissues." (PMID 31772678, 2019). "Our results showed six genes (p16, RASSF1A, GSTP1, APC, p15 and SFRP1) in HBV-positive carcinoma tissues, one gene (GSTP1) in HBV-positive adjacent tissues and two gene (p16 and APC) in HBV-positive carcinoma serums, which were significantly hypermethylated." (PMID 31772678, 2019). "The meta-analysis of GSTP1, RUNX3, SOCS1, CDH1 and SFRP1 genes methylation was performed between HBV-positive carcinoma tissues and HBV-negative carcinoma tissues and between HBV-positive adjacent tissues and HBV-negative adjacent tissues." (PMID 31772678, 2019). "The change in expression of BRCA1, GSTP1, PTEN, and others have been widely documented in various types of human cancers." (PMID 28199384, 2017). "EGCG is active against many types of cancer cells, demethylates and reactivates several genes involved in cancer like p16, RARβ, MGMT, hMLH1, and GSTP1." (PMID 26339624, 2015). "ABCB1, BRCA1, GSTP1, and IGF2 displayed both an increased CM fraction and hyper-methylation in cancer." (PMID 26659027, 2015). "In these cancers, the methylation of the promoter regions of tumor suppressor genes, such as CDH1, APC, MGMT, RASSF1A, GSTP1, p16 and RAR-β2, affect the activity of tumor suppressor genes, typically leading to transcriptional silencing." (PMID 24748968, 2014). "Stable overexpression of GSTP1 and CBR1 in cancer cells also reduces PL-induced ROS levels and rescues apoptosis." (PMID 25193861, 2014). "Although, promoter methylation of p16, DAPK, GSTP1 and BRCA1 genes are frequent events in several carcinomas, including ESCC, but very few studies considered these genes together in ESCC." (PMID 23596512, 2013). "In total, 1,009 genes were prone to hypermethylation by this analysis in at least one type of cancer, including a number reported to be frequently hypermethylated in cancer (for example, APC, DAPK1, ESR1, GSTP1, SFRP genes and HOX genes)." (PMID 23034185, 2012). "Consistent with our results, other studies have also described quantitatively much less promoter methylation of GSTP1 in BPH and histologically normal tissue (from tumour containing prostates) than in cancer specimens." (PMID 17453001, 2007). "However, there have been a number of studies designed to address the effects of GST genotypes on survival and secondary malignancies after treatment for cancer, with several – although not all – studies finding an important role for GSTP1 polymorphisms in treatment outcomes." (PMID 16848913, 2006). "Specifically, all three other genes found to be coordinately hypermethylated with GSTP1 in this study, APC, RARB2, and RASSF1A, are established as functionally important in other cancers." (PMID 15292941, 2004). "Hypermethylation frequencies for GSTP1, RARB2, RASSF1A, and APC in carcinoma tissues were each >70%, strongly correlating with each other (P<10−6)." (PMID 15292941, 2004). "Nonetheless, we still did some virtual screening work to search for GSTP1 inhibitors as it is particularly promising in the context of cancer therapy, not just for AD treatment." (PMID 40186323, 2025). "Investigating other SMURF2 targets and interactions with GSTP1 within the TME, especially involving immune cells, could further elucidate its role in cancer survival and unveil new immunotherapeutic opportunities." (PMID 39697237, 2024). "A reduced cancer risks was found among nondrinkers with GSTP1 (AG + GG) variations (I2 = 0.00%, OR = .840, 95% CI: 0.717–0.985, P = .032)." (PMID 38579033, 2024). "However, in the case of cancer cells, the downregulation of PRMT6 leads to an increased production of GSTP1." (PMID 38686048, 2024).
cancer (continued). "Whether and how GSTP1 regulates cardinal lung CSC properties, including stemness, aggressiveness, and resistance to non‐substrate anti‐cancer treatment are still unknown." (PMID 36709476, 2023). "This correlation between CYP1A1, GSTM1, GSTP1, and GSTT1 seems to be important, once this balance between activation and detoxification of carcinogens can influence the development, progression, and prevention of cancer." (PMID 35409669, 2022). "Among subjects without cancer, we found a significant correlation between participant age and GSTP1 expression." (PMID 35409669, 2022). "We conclude that, while many p63-positive cancers are also positive for GSTP1, most GSTP1-positive cancers are not p63-positive." (PMID 34191807, 2021). "The percentage of adenocarcinomas from Black patients who had any GSTP1 positive cancer-containing TMA cores was 14.9%, which was 2.5 times higher than the percentage of cases with any GSTP1 positive cancer-containing cores from White patients (5.9%; P < 0.001)." (PMID 34191807, 2021). "In contrast, the percentage of patients with ERG negative cancers that were GSTP1 positive was more similar in Black (12.9%) and White (9.4%) patients (P = 0.38)." (PMID 34191807, 2021). "In Black patients, the opposite pattern was observed; the percentage of any TMA spot positive for GSTP1 expressing cancer was higher in men who were ERG positive than ERG negative." (PMID 34191807, 2021). "From these group of genes, XPC, GSTP1, and ITGA5 were validated on breats cancer samples from TCGA." (PMID 32078659, 2020). "Our results suggest that GSTP1 methylation in negative prostate biopsies is stable over time and can predict missed cancer with high specificity." (PMID 31666119, 2019). "The studies focused on GSTP1-1 and its relationships with cancer biology were not limited to finding a way to inhibit the enzymatic activity or modulate the apoptotic pathway with the development of different compounds." (PMID 31357662, 2019). "In conclusion, our data suggest that GSTP1 methylation in negative prostate biopsies is stable over time and can predict missed cancer with high specificity." (PMID 31666119, 2019). "We found a statistical difference between HBV-positive carcinoma tissues and HBV-negative carcinoma tissues for GSTP1 methylation in China from six studies (OR = 2.13, 95% CI = 1.13-4.03, I2 = 0%, p = 0.02) and in Japan from five studies (OR = 4.29, 95% CI = 1.62-11.41, I2 = 0%, p = 0.003)." (PMID 31772678, 2019). "Variability of GSTP1 expression does not correlate with high‐grade cancer or invasive‐stage (p > 0.05)." (PMID 30043549, 2018). "Overall, these findings can explain why overexpression of GSTP1-1 has extensively been linked with the resistance to apoptosis and chemoresistant phenotype of different solid cancers, even when certain anti-cancer drugs are not GSTP1 substrates." (PMID 30487385, 2018). "Seven out of 52 genes (GSTP1, HSP90B1, HSPB1, PFN1, RAP1A, SFN, YWHAZ) were assigned to KEGG pathways in cancer, cell migration and cell cycle, and in signaling networks involved in proliferation, cellular motility, apoptosis, cell adhesion, angiogenesis and genetic integrity." (PMID 30157864, 2018). "In BC cases, GSTP1 expression was strong in 23.33% (7/30), moderate in 60% (18/30), and weak in 13.33% (4/30) of cases, while GSTP1 was not expressed in one cancer case (3.33%)." (PMID 30043549, 2018). "Glutathione-S-transferase pi 1 (GSTP1) is demonstrated to inhibit Cdk5 activity directly by binding to Cdk5 and dislodging p25/p35, and indirectly by suppressing oxidative stress-induced Cdk5 hyperactivation in neuronal and cancer cells." (PMID 28288624, 2017). "Notably, a combination of GSTP1, RARß2, RASSF1a, and APC has been the best at discriminating cancer from non-cancer specimens." (PMID 27835705, 2016).
cancer (continued). "Previous studies mainly focus on the cytotoxic effects of PL in cancer cells and various ROS-dependent cell death mechanisms, e.g., apoptosis, autophagic cell death, cell cycle arrest, GSTP1, p38, JNK, Erk, which have been proposed in different cancer cell lines." (PMID 25788268, 2015). "Here, in this study, we analyzed the aberrant promoter methylation profile of HNSCC using seven important tumor-related pathway genes (p16, DAPK, GSTP1, ECAD, RASSF1, MLH1 and BRCA1) and three methylated loci (MINT1, MINT2 and MINT31) in the high cancer incidence zone of Northeast India." (PMID 26098903, 2015). "Hypermethylation of APC, CCND2, GSTP1, PTGS2 and RARB was highly cancer-specific." (PMID 26086362, 2015). "Studies comparing NTAT with benign prostate tissue and/or cancer tissue identified alterations in gene expression, telomere DNA content, mitochondrial DNA, and prevalence of methylation in some genes, including APC, GSTP1 and RARβ2." (PMID 23874531, 2013). "Here, we studied promoter methylation status of key tumour suppressor genes involved in different cellular pathways and thought to be important in cancer development and progression, namely, p16 (cell cycle regulation), DAPK (apoptosis) BRCA1 (DNA repair) and GSTP1(protection of DNA)." (PMID 23596512, 2013). "To test this hypothesis, we evaluated a selected panel of SNPs in GSTP1, COMT, and TPMT with cancer outcome, ototoxicity, and peripheral neuropathy in an existing cohort of men with TGCT who have received at least one course of cisplatin-based chemotherapy." (PMID 23248619, 2012). "Regarding miR-133a in human cancers, our previous studies demonstrated that miR-133a functions as a tumor suppressor and targets multiple oncogenes, such as FSCN1, LASP1, CAV1 and GSTP1." (PMID 21378409, 2011). "This study provides further evidence of the transforming abilities of this oncoprotein, setting the groundwork for devising unique molecular tools that can both interfere with the interaction between HPV-16 E7 and GSTP1 and minimize the survival of HPV-16 E7-expressing cancer cells." (PMID 19826491, 2009). "Our findings align with and extend previous research on GSTP1 inhibition, such as studies involving ethacrynic acid (Tew and Gaté, 2001; Potęga 2022) and TLK199, which demonstrated the ability of these inhibitors to increase cancer cell sensitivity to chemotherapy." (PMID 39954068, 2025). "Our work implies that GSTP1 plays a dominant role linking G6PD and SRC to form a “signalosome” that provides a basis, under metabolic stresses, for robust cancer cell proliferation upon lactic acid signaling, which could regulate many aspects of cellular metabolism." (PMID 37491277, 2023). "Besides platinum drugs, the sensitivity to doxorubicin and various alkylating agents in cancer may also be affected by the detoxification process mediated by GSTA subclass, GSTP1, and GSTM1 enzymes." (PMID 37229486, 2023). "The non-hepatic GSTP1 isotype is abundantly expressed in some cancers and may be responsible for anticancer drug resistance by deactivating electrophilic drugs or by influencing cell signaling pathways." (PMID 34299488, 2021). "There is currently one validated epigenetic test commercially available, ConfirmMDx (MDxHealth, Irvine, CA, USA), designed for diagnostic rather than prognostic purposes, that uses the methylation profile of three genes (APC, RASSF1, GSTP1) to detect cancer in histologically negative biopsies." (PMID 33076494, 2020). "Additionally, GSTP1 plays a role as a modifier gene in the regulation of the molecular expression and activation of enzymes from other GST subfamilies and their effects on cancer, and GSTP1 expression regulates cellular redox homeostasis in carcinogenesis." (PMID 33634021, 2020).
cancer (continued). "Finally, we demonstrate that such turnover of cysteine oxidation and nEGFR function depends on the presence of glutathione S-transferase P 1 (GSTP1), a known catalyst of GSH conjugation to oxidized cysteines and an important determinant of metabolic dysfunction and pathogenicity in cancer." (PMID 30890751, 2019). "In six genes (p16, RASSF1A, GSTP1, APC, p15 and SFRP1), there was significant difference in the level of hypermethylation between HBV-positive carcinoma tissues and HBV-negative carcinoma tissues, revealing that HBV infection could induce methylation of these genes in HCC." (PMID 31772678, 2019). "No GSTP1 gene promoter methylation was detected in all control and cancer cases." (PMID 30043549, 2018). "Notably, the diagnostic accuracy of this signature was not simply driven by GSTP1, for which epigenetic cancer field effects have previously been demonstrated in PC." (PMID 28084441, 2017). "Eleven cancer related genes were found to have methylation (defined as more than 10 % methylation) in at least some of the tumours: RASSF1A (64 %), TWIST1 (61 %), CDH13 (51 %), APC (50 %), MAL (35 %), GSTP1 (30 %), WIF1 (26 %), RARβ (19 %), BRCA1 (2 %), CDKN2A (2 %) and TP73 (2 %)." (PMID 26452468, 2015). "However, knockdown of GSTP1 did not affect PL-induced ROS levels or death in cancer cells, and pharmacological inhibition of JNK or PARP did not completely abrogate PL-induced death." (PMID 25193861, 2014). "Furthermore, after comparing the matched adjacent non-HCC tissues, we suggest a cancer field effect of GSTP1 methylation." (PMID 22536438, 2012). "For example, to access information about the BRCA1 (breast cancer 1, early onset), GSTP1 (glutathione S-transferase pi) and ESR1 (estrogen receptor 1) gene methylation profile across various types of cancer, a user could input BRCA1, GSTP1, ESR1 as search terms separated by line breaks." (PMID 22168213, 2011). "Furthermore, the role of GSTP1 rs1138272 in other cancer types has not yet been investigated." (PMID 30740061, 2018). "However, using GSTP1 CpG island hypermethylation alone may not be able to distinguish PCa from other cancers, since GSTP1 CpG island hypermethylation has been reported in other cancers." (PMID 24086370, 2013). "Finally GSTP1 expression could potentially represent a good histological marker in substitution of or in addition to AMACR, p63, or cytokeratin, already used in clinical practice, so as to improve PCa detection when diagnosis is ambiguous due to the presence of cancer mimics such as PIN." (PMID 27594734, 2016). "It showed significantly higher frequencies of methylation of cancer-related genes (p14ARF, p15, p16INK4A, p73, TIMP3, E-cadherin, DAPK, and GSTP1) than EBV negative/ CIMP-H LLC, except for the methylation of hMLH1, and MGMT." (PMID 24188515, 2013). "GSTP1, RARB2, APC, and RASSF1A were each hypermethylated in 70–80% of carcinoma tissues, whereas the order in noncarcinoma tissues was RASSF1A>APC>GSTP1=RARB2." (PMID 15292941, 2004). "We did not observe differences in GSTM1, GSTP1, or GSTT1 gene expression in the cancer group, but as Phase II enzymes are responsible for detoxification of carcinogens, once cancer is present, it possibly means that the role of these enzymes is not proceeded to neutralize the toxic substances." (PMID 35409669, 2022). "Although GSTP1 has such promising features as a cancer-specific biomarker, it has not yet been applied in a clinical setting; although the specificity of GSTP1 promoter hypermethylation is much higher than that of prostate-specific antigen (PSA), the sensitivity of GSTP1 is lower than that of PSA." (PMID 33628338, 2021).